LOXL3 (lysyl oxidase like 3)
Diseases named in the same sentence as LOXL3 in open-access papers (continued):
Sharing a sentence is not in itself a finding about the gene and the disease.
cancer (27 papers, 2015 to 2025). A tumor composed of atypical neoplastic, often pleomorphic cells that invade other tissues. "By integrating currently available information, we aim to lay a theoretical groundwork for further investigation into LOXL3 as a potential prognostic biomarker, therapeutic target, and diagnostic marker in cancer." (PMID 41250755, 2025). "Meanwhile, numerous prognostic analyses have demonstrated that high LOXL3 expression is an independent risk factor for poor prognosis in cancer patients." (PMID 41250755, 2025). "Among these, LOXL3 is closely associated with cancer cell proliferation, invasion, and metastasis." (PMID 41250755, 2025). "Similarly, Renca cells showed dynamic expression changes of multiple genes across passages, including Btbd17, Loxl3, Raf1, and Acvrl1, which may be closely associated with signal transduction, transcriptional regulation, and cancer-related pathways." (PMID 41272245, 2025). "To comprehensively summarize the research progress in the field of LOXL3 and cancer, we conducted a systematic literature review using two major databases, PubMed and Web of Science, as the retrieval platforms." (PMID 41250755, 2025). "It specifically focuses on elucidating how LOXL3 contributes to pro-cancer activities across various tumors and its implications for related prognostic outcomes." (PMID 41250755, 2025). "On the other hand, high-throughput screening technology can be used to identify low-molecular-weight inhibitors from a large number of compounds, which can exert inhibitory effects on certain human cancers with elevated LOXL3 gene expression." (PMID 41250755, 2025). "LOXL3 demonstrates significant upregulation in various malignant tumors and plays a critical role in orchestrating core oncogenic processes during tumorigenesis and progression." (PMID 41250755, 2025). "Systematic molecular profiling across cancer types has confirmed the predominantly pro-tumorigenic functions of LOXL3, and multi-cohort clinical validations have established its strong prognostic value." (PMID 41250755, 2025). "Core search terms “LOXL3” and “Cancer” were combined using boolean operators for the literature search." (PMID 41250755, 2025). "Specifically, we detected elevated expression levels of Lox, Loxl1, and Loxl3 in mesenchymal cancer cells." (PMID 37156840, 2023). "Consistent with this, LOXL3-deficient cells exhibited elevated cell death and lower IC50 value which represented the lower chemoresistance status of cancer cells under the drug treatment." (PMID 37253718, 2023). "LOXL3 was also found to induce downregulation of Th17 and Treg activation as well which play a role in cancer pathogenesis." (PMID 35433829, 2022). "Initially, we investigated the expression of LOXL3 in 32 different types of cancer using 10,967 samples from the TCGA RNA-seq database." (PMID 34360836, 2021). "In order to explore the involvement of LOXL3 in cancer, we performed in silico analyses of public data sets." (PMID 29229995, 2018). "The carcinogenic function of LOXL3 across multiple human cancer." (PMID 41250755, 2025). "These inhibitors can block the function of LOXL3 at the protein functional level, complementing the regulation at the gene level, and collectively providing support for the targeted therapy of related cancers." (PMID 41250755, 2025). "Such patients usually have shorter progression-free survival (PFS) and overall survival (OS), suggesting that LOXL3 may serve as a potential biomarker for evaluating cancer prognosis." (PMID 41250755, 2025). "Additionally, the N-terminal SRCR sequence of LOXL3 possesses deacetylase activity, which impedes differentiation mediated by STAT3in both normal and cancer cells by reducing STAT3 acetylation." (PMID 39247609, 2024). "This could help cancer cells to resist chemotherapy-induced lipid peroxidation and ferroptosis, possibly via the LOXL3/DHODH axis." (PMID 37253718, 2023).
cancer (continued). "However, this is the first report of correlation of LOXL3 with β-catenin expression level in cancer." (PMID 36076905, 2022). "Regarding cancer, few reports have involved LOXL3 in human cancer." (PMID 35267510, 2022). "High LOXL3 expression levels were detected in 10 types of cancer, including GBM (in red)." (PMID 34360836, 2021). "Thus far the reported roles for LOXL3 were essentially associated with LOXL3 extracellular activity regarding ECM maturation, whereas LOXL3 involvement in cancer remains limited." (PMID 29229995, 2018). "However, studies concerning LOXL3 in cancers are quite limited." (PMID 33058284, 2020). "Concerning cancer cell lines, the expression of LOX, LOXL1, LOXL2, LOXL3 and LOXL4 was highest in GBM, GBM, GBM, SKCM and PAAD, while lowest in CLL, CLL, LCML, DLBC and CLL, respectively." (PMID 40179101, 2025). "Another study showed that lysyl oxidase-like 3 (LOXL3) inhibits ferroptosis and fosters chemoresistance in cancer cells by stabilizing DHODH, unveiling a regulatory mechanism in the DHODH-mediated ferroptosis defense." (PMID 38428031, 2024). "LOX family members (LOX, LOXL1, LOXL2, LOXL3, LOXL4) reportedly mediate cell migration and metastasis of different cancers." (PMID 34815382, 2021). "Thus, the genes LOXL3, ADAM19, FBN2, and RND3 are associated with cancer relevant biological processes such as loss of adhesion, proliferation, migration and metastasis and are therefore might be functionally related to CLIP2 in the context of radiation induced PTC-carcinogenesis of PTC." (PMID 32727620, 2020). "For example, LOX, LOXL2, LOXL3, and LOXL4 are overexpressed in more invasive cancers, such as triple negative breast cancers, inducing cancer cell invasion and metastasis." (PMID 32984031, 2020). "The role of LOXL2 in fibrosis and cancer is well documented, however the specific enzymatic function of LOXL2 and LOXL3 during disease is less clear." (PMID 30536539, 2019). "This family comprises five cooper-dependent amine oxidases (LOX, LOXL1, LOXL2, LOXL3, and LOXL4), which are involved in several hallmarks of cancers, such as tumor microenvironment remodeling, invasion/migration, growth, inflammatory response, genomic stability, and resistance to chemotherapy." (PMID 36076905, 2022). "Regarding LOXL3, substantial information reinforces its role in ECM remodeling linking deregulated LOXL3 to different connective tissue disorders; however, LOXL3 involvement in cancer has not been systematically investigated." (PMID 29229995, 2018). "However, the role of LOXL3 in cancer has not been fully elucidated; thus, inhibitors or monoclonal antibodies that specifically target LOXL3 have not been developed." (PMID 37253718, 2023). "In addition, we observe that LOXL3 is expressed by the circumferent myoepithelial cells in ductal carcinoma in situ (DCIS), but not by the carcinoma cells." (PMID 35292774, 2022).
connective tissue disorder (2 papers, 2018 to 2022). A disease involving the connective tissue. "Deregulated LOXL3 has been linked to several connective tissue disorders, consistent with the well-established role of lysyl oxidases as extracellular matrix enzymes contributing to tissue homeostasis." (PMID 35267510, 2022).
LOXL3 also shares sentences with these, for which no sentence is quoted: Hearing impairment (2 papers); infection (2); invasive breast carcinoma (2); Arthritis (1); autosomal recessive Stickler syndrome (1); breast tumours (1); cardiac disease (1); cardiomyopathy (1); chondrosarcoma (1); Cirrhosis (1); dysplastic nevi (1); Dyssegmental dysplasia, Silverman-Handmaker type (1); Hodgkins lymphoma (1); invasive ductal carcinoma (1); melanoma in situ (1); metastatic colorectal cancer (1); Micrognathia (1); myeloproliferative tumors (1); myocardial infarction (1); nevus (1); oral diseases (1); renal carcinoma (1); stomach cancer (1); triple-negative breast carcinoma (1); viral infection (1).